FKBP10 (FKBP prolyl isomerase 10)
Description:
PPIases accelerate the folding of proteins during protein synthesis.
Synonyms: FKBP65; hFKBP65; FLJ22041; FKBP6; FLJ20683; FLJ23833; BRKS; BRKS1; OI11; OI6; PPIASE; TLH1
Tractability: Small molecule: it belongs to a druggable protein family. Antibody: UniProt predicts a signal peptide or a membrane-spanning region. PROTAC: ubiquitination databases record sites on it; its protein half-life has been measured.
Gene: Protein-coding gene on chromosome 17 (41,812,680 to 41,823,221, forward strand). Ensembl gene ENSG00000141756.
Subcellular location: Endoplasmic reticulum lumen
Subcellular location (Human Protein Atlas): Golgi apparatus
Gene Ontology:
Molecular function: protein binding; FK506 binding; peptidyl-prolyl cis-trans isomerase activity; calcium ion binding
Biological process: protein folding
Cellular component: endoplasmic reticulum; endoplasmic reticulum lumen; membrane; mitochondrial intermembrane space
Genetic constraint (gnomAD): Loss-of-function variants: 34 observed, 55.3 expected, observed/expected ratio (o/e) 0.61, 90% interval 0.47 to 0.82. The upper end of that interval is the gene's LOEUF score, 0.82, which puts it in group 3 of 6, group 1 being the genes least tolerant of losing a copy. Missense variants: 748 observed, 826.45 expected, observed/expected ratio (o/e) 0.91, 90% interval 0.85 to 0.96. Synonymous variants: 324 observed, 349.6 expected, observed/expected ratio (o/e) 0.93, 90% interval 0.85 to 1.02.
Homologues: Orthologues: chimpanzee FKBP10 (99% identical), macaque FKBP10 (98% identical), pig FKBP10 (93% identical), dog FKBP10 (92% identical), mouse Fkbp10 (89% identical), rat Fkbp10 (87% identical), guinea pig FKBP10 (86% identical), rabbit FKBP10 (70% identical), tropical clawed frog fkbp10 (70% identical), zebrafish fkbp10b (58% identical), zebrafish fkbp10a (56% identical), Caenorhabditis elegans fkb-5 (13% identical), and 2 more. Paralogues in human: FKBP9 (55% identical), FKBP5 (14% identical), FKBP4 (14% identical), FKBP15 (13% identical), FKBP3 (12% identical), FKBP14 (11% identical), FKBP7 (11% identical), FKBP11 (10% identical), FKBP2 (9% identical), FKBP1A (9% identical), FKBP8 (9% identical), FKBP1C (9% identical), and 6 more.
Diseases named in the same sentence as FKBP10 in open-access papers:
FKBP10 is named in the same sentence as 64 diseases in open-access papers, as found by Europe PMC text mining. Sharing a sentence is not in itself a finding about the gene and the disease. The quoted sentences say what the papers report.
osteogenesis imperfecta (19 papers, 2011 to 2026). Osteogenesis imperfecta (OI) comprises a heterogeneous group of genetic disorders characterized by increased bone fragility, low bone mass, and susceptibility to bone fractures with variable severity. "FKBP10 mutation causes collagen-related illnesses such as osteogenesis imperfecta by decreasing collagen secretion." (PMID 37511172, 2023). "Bruck Syndrome (BRKS) is a rare type of recessive osteogenesis imperfecta (OI) and consists of two subtypes, BRKS1 and BRKS2, which are caused by variations in FKBP10 and PLOD2 genes, respectively." (PMID 33664768, 2021). "In family G5, two mutations were detected, for which both parents were carriers: one mutation in PCCA causing propionic acidemia, and another mutation in FKBP10 causing osteogenesis imperfecta; both are AR conditions." (PMID 30787035, 2019). "FKBP10 play an important role in human tissue homeostasis because mutations in this gene cause a severe form of osteogenesis imperfecta." (PMID 27689402, 2016). "Mutations in the FKBP10 gene were first described in patients with Osteogenesis imperfecta type III." (PMID 22107750, 2011). "Our study demonstrates that FKBP10 mutations not only cause Bruck syndrome or Osteogenesis imperfecta type III but can result in a severe type of isolated Osteogenesis imperfecta type IV with prenatal onset." (PMID 22107750, 2011). "Therefore, we conclude that FKBP10 mutations are a cause of recessive osteogenesis imperfecta and Bruck syndrome, possibly Bruck syndrome Type 1 since the location on chromosome 17 has not been definitely localized." (PMID 20839288, 2011). "FKBP10 was first thought to be involved in diseases such as idiopathic pulmonary fibrosis and osteogenesis imperfecta." (PMID 34388114, 2021). "Thecause of osteogenesis imperfecta of the X and XI types isa violation of the processing and cross-linking of collagendue to mutations in the SERPINH1 and FKBP10 genes, respectively.Mutations in the PLOD2 and BMP1 genes lead toincomplete type XII osteogenesis." (PMID 33659802, 2020). "Osteogenesis imperfecta type XI (OI-XI), is caused by a bi-allelic mutation of FKBP10 gene that results in a defect of FKBP65 protein production that leads to a delayed type I procollagen secretion and accumulation in the endoplasmic reticulum." (PMID 41530856, 2026).
Bruck syndrome (16 papers, 2011 to 2024). Bruck syndrome is characterized by the association of osteogenesis imperfecta and congenital joint contractures. "Mutations in the gene that encodes FKBP65, FKBP10, cause either recessive type XI OI, Bruck syndrome or Kuskokwim syndrome." (PMID 39127989, 2024). "On other hand, mutations in FKBP10 were shown to be a cause of Bruck syndrome, a rare recessive disorder similar to OI, characterized with congenital joint contractures, bone fragility, osteoporosis and short stature." (PMID 39127989, 2024). "Recent study showed that novel variants in FKBP10 caused Bruck syndrome with orodental changes such as dental malocclusion and enamel hypoplasia." (PMID 39127989, 2024). "Patients with contractures will be scanned for presence of variants in the PLOD2 and FKBP10 genes to specify presence of a Bruck syndrome diagnosis." (PMID 31447884, 2019). "Bruck Syndrome is a connective tissue disease associated with inactivating mutations in lysyl hydroxylase 2 (LH2/PLOD2) or FK506 binding protein 65 (FKBP65/FKBP10)." (PMID 28378777, 2017). "Hypofunction of FKBP10 protein induced by FKBP10 mutation reduced collagen formation, promoted bone fragility or joint contracture, and thus caused several severe diseases such as osteogenesis imperfect, Bruck syndrome." (PMID 33557829, 2021). "Thus, taken together, the previously reported patients and the family described here demonstrate that FKBP10 can cause either Bruck syndrome or isolated OI." (PMID 22107750, 2011). "In contrast to the patients with FKBP10 mutations described by Alanay and colleagues, the patients presented in these studies demonstrated a high incidence of congenital large joint contractures consistent with the diagnosis of Bruck syndrome." (PMID 20839288, 2011). "FKBP10 is localized to chromosome 17q21.2 different than the preliminary localization for the original type I Bruck syndrome family." (PMID 20839288, 2011). "Subject: Letter to the editor of Heliyon re: A novel compound heterozygous variation in the FKBP10 gene causes Bruck syndrome without congenital contractures: A case report." (PMID 39641041, 2024).
lung carcinoma (11 papers, 2021 to 2025). "In lung cancer, gain- and loss-of-function assays show that FKBP10 boosts cancer growth and stemness via its peptidyl-prolyl-cis-trans-isomerase (PPIase) activity." (PMID 39684755, 2024). "It has also been reported that FKBP10 is a cancer-selective molecule with a key role in translational reprogramming, stem-like traits, and growth of lung cancer." (PMID 37201304, 2023). "FKBP10 was connected with gastric cancer, stomach adenocarcinomas, papillary thyroid cancer, and lung cancer." (PMID 36675710, 2022). "Previous studies have shown that FKBP10 is located in the ER in lung cancer cells." (PMID 39781460, 2025). "In the study of a mouse lung cancer model, it was found that the low expression of the FKBP10 protein could inhibit the occurrence of lung cancer." (PMID 39474271, 2024). "In lung cancer, FKBP10 is selectively expressed and negatively correlated with patients’ outcomes." (PMID 37511172, 2023). "Further analysis of the CANCERTOOL database revealed that the expression of FKBP10 was similar between lung adenocarcinoma bearing mutant KRAS, EGFR, and KRAS/EGFR non-mutants, suggesting that the relevance of FKBP10 in lung cancer is not limited to a specific genotype." (PMID 37201304, 2023). "These lines of evidence indicate that FKBP10 may be a lung cancer-specific biomarker in primary lesions and brain metastases." (PMID 37201304, 2023). "For example, overexpression of FKBP10 promoted lung cancer growth in vitro or in vivo, indicating that this gene might be a putative therapeutic target for lung cancer." (PMID 36463181, 2022). "In contrast, FKBP10 expression was significantly correlated with NR2F6 expression in specimens from patients with melanoma, pancreatic, and lung cancer, suggesting the requirement of TME components for the NR2F6 control of tumor-intrinsic FKBP10 expression." (PMID 37406115, 2023). "FKBP10, an endoplasmic reticulum chaperone, coordinates protein translation to sustain lung cancer growth, but the mechanism of action in CC has not been elucidated." (PMID 36341424, 2022).
clear cell renal cell carcinoma (10 papers, 2021 to 2026). "Through its facilitation of LDHA phosphorylation, FKBP10 enhances the advancement of clear cell renal cell carcinoma and controls susceptibility to HIF2α inhibition." (PMID 39968078, 2025). "Our research has proven that FKBP10 can promote the proliferation and metastasis of renal clear cell carcinoma, and it depends on its own PPIase functional domain." (PMID 38233415, 2024). "High VSX1 expression promotes the aggressiveness of clear cell renal cell carcinoma through transcriptional regulation of FKBP10." (PMID 39023752, 2024). "Additionally, FKBP10 promotes clear cell renal cell carcinoma progression and modulates HIF2α blockade sensitivity by facilitating LDHA phosphorylation." (PMID 41454479, 2026). "Therefore, our study demonstrates that FKBP10 promotes clear cell renal cell carcinoma progression and regulates sensitivity to HIF2α blockade by facilitating LDHA phosphorylation, which may be exploited for anticancer therapy." (PMID 38233415, 2024). "Additionally, overexpression of VSX1 has been shown to increase the activity of TMEM44, FKBP10, and TRIB3, and enhance the growth of renal clear cell carcinoma." (PMID 37561335, 2024).
gastric cancer (10 papers, 2021 to 2024). A primary or metastatic malignant neoplasm involving the stomach. "More abundant FKBP10 has been detected and has revealed correlations with poor prognosis in gastric cancer, stomach adenocarcinoma and CRC." (PMID 37511172, 2023). "FKBP10 is overexpressed in renal cancer, glioma and gastric cancer, where it promotes tumor cell proliferation, invasion and migration." (PMID 37511172, 2023). "It has been demonstrated that FKBP10 expression contributes to the development of colorectal, lung, renal cell, and stomach cancers." (PMID 37124542, 2023). "The IFITM family may also be mutated in gastric cancer, regulating the entry of viruses into host cells, activating IFI6 and FKBP10 and leading to TF phosphorylation like STAT1." (PMID 39228892, 2024). "FKBP10 might play an important role in the development of gastric cancer through cell adhesion molecules and extracellular matrix receptors." (PMID 35395711, 2022). "Besides, FKBP10 upregulation has been observed in KRAS mutation-induced lung adenocarcinoma, colorectal cancer renal cell carcinoma, gastric cancer and knockdown of FKBP10 expression could reverse the malignant phenotype, especially proliferation ability." (PMID 33557829, 2021). "FKBP10 was also found to be upregulated in KRAS-mutant lung adenocarcinoma, renal cell carcinoma, and gastric cancer, and knockdown of FKBP10 is sufficient to hinder proliferation of tumor cells growth." (PMID 33557829, 2021). "The results of the meta-analysis and bioinformatics analysis suggested that FKBP prolyl isomerase 10 (FKBP prolyl isomerase 10, FKBP10) has significant value in the treatment of gastric cancer." (PMID 34506251, 2021). "In gastric cancer, elevated alpha-inducible protein 6 (IFI6) and FKBP prolyl isomerase 10 (FKBP10) could be responsible for the activation of STAT1 expression, diminishing antiviral responses." (PMID 39228892, 2024). "Transcriptional levels of FKBP10 and FKBP11 are upregulated in renal cell carcinoma tissues compared to normal tissues, and FKBP14 is involved in various types of human tumors such as gastric cancer, human cervical cancers, ovarian cancer, and osteosarcomas." (PMID 36675710, 2022). "Moreover, the immunohistochemistry results from HPA database showed that FKBP10 was upregulated in gastric cancer tissues, while ALDH3A2 and MAOA were downregulated in gastric cancer tissues, when compared with corresponding non-cancerous tissues." (PMID 36915111, 2023).
glioma (9 papers, 2021 to 2025). A benign or malignant brain and spinal cord tumor that arises from glial cells (astrocytes, oligodendrocytes, ependymal cells). "Quantitative reverse transcriptase-PCR, western-blotting, GST-pull down, co-immunoprecipitation and confocal-immunofluorescence staining assay were used to explore the molecular mechanism underlying the functions of overexpressed FKBP10 in glioma cells." (PMID 33557829, 2021). "Our data suggested that targeting FKBP10-associated signaling might be a promising strategy in the treatment of glioma." (PMID 33557829, 2021). "The authors have previously reported that FKBP10 is overexpressed in glioma and is involved in the proliferation of glioma cells by interacting with Hsp47 and activating AKT-CREB-PCNA signaling pathways." (PMID 37201304, 2023). "For example, circREEP3 upregulation recruited the chromatin remodeling protein CHD7 to activate FKBP10 transcription and drive colorectal cancer progression, and the FKBP10 protein was recognized as a glioma antigen for anti-glioma mRNA vaccine production." (PMID 36463181, 2022). "GST-pull down and liquid chromatography–mass spectrometry (LC–MS)/MS analyses showed that heat shock protein 47 (Hsp47) was preferentially bind to FKBP10 in glioma cells." (PMID 33557829, 2021). "Multivariate Cox regression analysis indicated that FKBP10 overexpression was an independent indicator for poor prognosis of grade 4 glioma patients." (PMID 33557829, 2021). "FKBP10 was highly expressed in glioma tissues and its expression was positively correlates with grade, poor prognosis." (PMID 33557829, 2021). "Four glioma antigens, namely ANXA5, FKBP10, MSN, and PYGL, associated with superior prognoses and infiltration of APCs were selected." (PMID 34512630, 2021). "We showed for the first time that FKBP10 is overexpressed in glioma and involved in proliferation of glioma cells by interacting with Hsp47 and activating AKT-CREB-PCNA signaling pathways." (PMID 33557829, 2021). "In vivo experiments showed that knockdown of FKBP10 in LN229 glioma cells significantly decreased the tumorigenic ability." (PMID 33557829, 2021). "The differentially expressed and mutational profile of glioma was constructed, and four targetable antigens (ANXA5, FKBP10, MSN, and PYGL) were further confirmed." (PMID 34512630, 2021). "CCK-8 tests, colony formation assays and xenograft model were performed to test proliferation ability of FKBP10 in glioma cells in vitro and in vivo." (PMID 33557829, 2021). "Studies have reported that FKBP10 participates in the proliferation of glioma cells via interacting with Hsp47 and activating the AKT-CREB-PCNA axis." (PMID 34512630, 2021). "Knockdown of FKBP10 expression in glioma cells led to a significant reduce of cell proliferation rate and colony number compared to the control cells." (PMID 33557829, 2021). "Western-blot and immunocytochemistry analyses of 10 glioma cell lines showed that high FKBP10 expression was in T98G, U118MG, LN229, U343MG and HS683, and located in cellular cytoplasm." (PMID 33557829, 2021). "In the present study, we firstly detected FKBP10 interacting with Hsp47 in glioma cells and concomitant expression between FKBP10 and Hsp47 in glioma tissues." (PMID 33557829, 2021). "Strong FKBP10 immunostaining was positively related to poor prognosis in both grades 3 (HR = 2.06, 95% CI 1.08–3.91, P = 0.024) and 4 gliomas (HR = 1.80, 95% CI 1.27–2.52, P = 0.0007)." (PMID 33557829, 2021). "In coincidence with these observations, our study showed that FKBP10 highly expressed in glioma tissues, and knockdown of FKBP10 could inhibit the proliferation of glioma cells both in vitro and in vivo." (PMID 33557829, 2021). "Additionally, gliomas with high FKBP10 expression tend to own high expression level of p-CREB (Ser133) and PCNA (P = 1.57E-9 and 0.0009, respectively)." (PMID 33557829, 2021). "High FKBP10 expression was an independent indicator for poor prognosis of grade 4 glioma patients." (PMID 33557829, 2021).
glioma (continued). "Thus, it will be important to explore the targeted therapy of glioma based on the alterations of FKBP10 and Hsp47." (PMID 33557829, 2021). "Inhibiting tumor progression by inhibiting FKBP10-related signals may provide a potential treatment option for glioma." (PMID 34512630, 2021). "Our findings suggest that inhibition of FKBP10 related signaling might offer a potential therapeutic option for glioma patients." (PMID 33557829, 2021). "Future studies should explore whether abolishing the interaction of FKBP10/Hsp47 could enhance the sensitivity to TMZ in the therapy of glioma." (PMID 33557829, 2021). "Herein, we first demonstrate that FKBP10 is probably a potential target for the therapy of glioma." (PMID 33557829, 2021). "In the present study, we found that FKBP10 was upregulated in glioma." (PMID 33557829, 2021). "Moreover, FKBP10 promoted proliferation of glioma cells through AKT-CREB-PCNA signaling and might be as a possible therapeutic target for glioma." (PMID 33557829, 2021). "Furthermore, in view of the overexpression and interaction of FKBP10 and Hsp47 as well as the effect of FKBP10 on the proliferation of glioma cells, the present study might provide potential targets for the therapy of the disease." (PMID 33557829, 2021). "Four glioma antigens were identified, including FKBP prolyl isomerase 10 (FKBP10), glycogen phosphorylase L (PYGL), annexin A5 (ANXA5), and moesin (MSN), which were correlated with elevated APC infiltration and better prognoses." (PMID 40948290, 2025). "However, biological role of FKBP10 in glioma remains unclear." (PMID 33557829, 2021). "Tissue microarrays and immunohistochemistry were used to detect FKBP10, Hsp47, p-AKT (Ser473), p-CREB (Ser133) and PCNA expression in glioma tissues and xenografts." (PMID 33557829, 2021). "The amplified expressions of ANXA5, FKBP10, MSN, and PYGL were correlated with favorable prognosis OS and DFS of glioma, which exert pivotal roles in glioma development and progression." (PMID 34512630, 2021). "Immunochemistry analysis showed that FKBP10 was undetectable in all the tested non-neoplastic tissues, but strongly expressed in 5.4%, 40.0% and 64.7% of grades 2, 3, 4 gliomas, with an increasing frequency in higher grade tumors." (PMID 33557829, 2021). "Especially, we observed that FKBP10, via interacting with Hsp47, increased the phosphorylation level of AKT at Ser473 and CREB at Ser133, which promoted the transcription of PCNA and the proliferation of glioma cells." (PMID 33557829, 2021). "All these results suggest that FKBP10 interacted with Hsp47, promoted the phosphorylation of AKT and CREB, upregulated the expression of PCNA mRNA and PCNA protein level, and thus enhanced the proliferation ability of glioma cells." (PMID 33557829, 2021). "Four antigens ANXA5, FKBP10, MSN, and PYGL were promising to develop mRNA vaccine against glioma." (PMID 34512630, 2021).